FKBPL (FKBP prolyl isomerase like)
Diseases named in the same sentence as FKBPL in open-access papers (continued):
Sharing a sentence is not in itself a finding about the gene and the disease.
preeclampsia (continued). "We further show that cardiac spheroids containing cardiac fibroblasts and endothelial cells, treated with plasma from women with early- or late-onset preeclampsia, express higher protein levels of FKBPL reflective of early restricted angiogenesis." (PMID 33879252, 2021). "The CD44/FKBPL ratio was reduced in placenta and plasma following clinical diagnosis of preeclampsia." (PMID 32617576, 2021). "A novel anti-angiogenic protein, FKBPL, is emerging as having a potential role in both preeclampsia and cardiovascular disease (CVD)." (PMID 33879252, 2021). "The CD44/FKBPL ratio was also capable of diagnosing preeclampsia and was differentially expressed in placentae affected by preeclampsia." (PMID 32617576, 2021). "Our results demonstrated increased FKBPL protein expression (>1.5-fold) in preeclampsia cases compared to controls (P < 0.05, n = 4)." (PMID 32617576, 2021). "At 20 weeks of gestation, a high CD44/FKBPL ratio and high MAP were associated with an approximately 4-fold increased risk of preeclampsia." (PMID 32617576, 2021). "Recent studies show that FKBPL regulates inflammatory STAT3 signalling, via CD44 and NFkB, which are both implicated in preeclampsia." (PMID 33879252, 2021). "The combined effect of the CD44/FKBPL ratio and MAP (cut-off = 82.5 mmHg; AUC = 0.648, P = 0.004; sensitivity = 0.62, specificity = 0.59), on the risk of developing preeclampsia was investigated using multinomial logistic regression models." (PMID 32617576, 2021). "Consequently, this indicates that the CD44/FKBPL intensity ratio is considerably lower in cases of early-onset preeclampsia when compared to the control group." (PMID 39744682, 2025). "In cardiovascular disease context, AD-01 was able to restore angiotensin-II-induced cardiac hypertrophy via negative regulation of FKBPL, which could make it useful for preeclampsia treatment although its safety in pregnancy is unknown." (PMID 40109359, 2025). "Furthermore, there was a significant positive correlation between plasma FKBPL and preeclampsia (r = 0.578, p < 0.001), even when adjusted for differences in gestational age and BMI (r = 0.559, p < 0.001)." (PMID 36652019, 2023). "In our previous study, we observed that plasma FKBPL was reduced early in pregnancy (15-week gestation) in women who proceeded to develop preeclampsia, while following diagnosis FKBPL was significantly increased in plasma and placentae compared to healthy controls." (PMID 36652019, 2023). "We also validated this model by evaluating the emerging FKBPL and Gal-3 inflammatory and anti-angiogenic mechanisms in placental development and growth, compared to their secretion and expression in plasma and placental samples from women with preeclampsia." (PMID 36652019, 2023). "Notably, hypoxia as a pro-angiogenic stimulus, which is present in the ischemic placenta in preeclampsia, led to a reduction in endothelial and trophoblast FKBPL protein and mRNA expressions and a concomitant increase in CD44 mRNA expression." (PMID 32617576, 2021). "While we have shown FKBPL to be more highly expressed in women with preeclampsia compared with healthy controls, its relationship and role in cardiovascular health in preeclampsia is unknown." (PMID 33879252, 2021). "To address this hypothesis, we demonstrated that FKBPL is differentially secreted early in pregnancy (weeks 15 and 20 of gestation) in women who proceeded to develop preeclampsia." (PMID 32617576, 2021). "The CD44/FKBPL ratio could also identify the cases of evolving preeclampsia through longitudinal changes potentially leading to early detection of this condition." (PMID 32617576, 2021). "In the future, CD44 and FKBPL plasma concentrations should be investigated in a larger cohort of patients using longitudinal plasma samples from all three trimesters and postdiagnosis of preeclampsia." (PMID 32617576, 2021). "Elucidation of these novel FKBPL mechanisms in cardiac health in preeclampsia could be key in preventing future CVD." (PMID 33879252, 2021).
preeclampsia (continued). "FKBPL is also increased in plasma and placentae from women with preeclampsia." (PMID 33879252, 2021). "We have previously shown that the FKBPL plasma levels are reduced before the onset of preeclampsia and that low FKBPL levels lead to vascular dysfunction hence downregulation of FKBPL in T1D may lead to vascular dysfunction and preeclampsia." (PMID 34149611, 2021). "Plasma FKBPL concentration was reduced at both 15 and 20 weeks of gestation whereas plasma CD44 concentration was increased at 20 weeks of gestation in a low-risk cohort of women who proceeded to develop preeclampsia." (PMID 32617576, 2021). "However, as our previous work has shown, preeclampsia is characterized by an anti-angiogenic phenotype driven by the upregulation in FKBPL expression or increase in sFlt-1, which would disrupt this primary hypoxia defence mechanism triggered by reduced perfusion." (PMID 35064159, 2022). "Therefore, it appears that circulating factors, likely inflammatory, in maternal plasma during preeclampsia may induce an overexpression of FKBPL in cardiac fibroblast and/or endothelial cells." (PMID 33879252, 2021). "However, the FKBPL plasma concentrations were significantly lower (0.72 [0.52-1.10], n = 61 vs 1.0 [0.59-1.30], n = 59; P = 0.03), at 15 weeks of gestation in women who proceeded to develop preeclampsia." (PMID 32617576, 2021). "Therefore, a hypoxia-induced pro-angiogenic effect that drives FKBPL levels down could lead to endothelial dysfunction and hence the development of preeclampsia." (PMID 32617576, 2021). "Our recent research has revealed FKBPL and its target protein, cluster of differentiation 44 (CD44), as a new mechanism in the pathogenesis of preeclampsia." (PMID 41285723, 2025). "The biomarkers FKBPL and CD44 have been identified as potential indicators for predicting and diagnosing preeclampsia." (PMID 39744682, 2025). "Here, we first confirm the abnormal expression of important vascular and inflammatory proteins, FK506-binding protein-like (FKBPL) and galectin-3 (Gal-3), in human plasma and placental tissues from women with preeclampsia and normotensive controls." (PMID 36652019, 2023). "Placental expression of FKBPL, CD44, intercellular adhesion molecule (ICAM), and vascular cell adhesion molecule (VCAM) from women with preeclampsia were compared to their normotensive controls (matched for age, BMI, and gestational age)." (PMID 32617576, 2021). "Both FKBPL and CD44 are regulated by hypoxia and appear to have key roles in the processes important for SUA remodeling preceding the onset of preeclampsia." (PMID 32617576, 2021). "Interestingly, in established preeclampsia, the CD44/FKBPL ratio showed an opposite pattern, suggesting that these potential longitudinal changes in CD44/FKBPL ratio from trimester 2 to 3 could reflect evolving preeclampsia and, therefore, could be explored for early diagnosis." (PMID 32617576, 2021). "FKBPL and CD44 plasma concentration or placental expression were determined in women pre- or postdiagnosis of preeclampsia." (PMID 32617576, 2021). "FKBPL was increased in the hearts of RUPP rats and cardiac spheroids treated with plasma from women with preeclampsia, perhaps reflective of restricted angiogenesis and inflammation in this disorder." (PMID 33879252, 2021). "Therefore, in this study we aimed to characterise cardiac health and FKBPL regulation in the rat reduced uterine perfusion pressure (RUPP) and a 3D cardiac spheroid model of preeclampsia." (PMID 33879252, 2021). "However, the trend in FKBPL/CD44 expression levels is the same in placentae from Cohort 2 and plasma samples from Cohort 1, both of which are postdiagnosis of preeclampsia." (PMID 32617576, 2021). "The potential of FKBPL as a prognostic biomarker has been previously discussed in relation to other pathologies such as cancer, but not in the context of preeclampsia." (PMID 32617576, 2021).
preeclampsia (continued). "In addition, we have recently shown the increased expression of FKBPL in the hearts of pregnant rats with reduced uterine perfusion pressure (RUPP), an in vivo model of preeclampsia, and cardiac spheroids treated with plasma from women with preeclampsia." (PMID 36652019, 2023).
endothelial dysfunction (6 papers, 2020 to 2025). In vascular diseases, endothelial dysfunction is a systemic pathological state of the endothelium (the inner lining of blood vessels) and can be broadly defined as an imbalance between vasodilating and vasoconstricting substances produced by (or acting on) the endothelium. "Moreover, the high FKBPL expression in HUVECs, evoked by plasmid vector transfection, was associated with a reduction in tubule formation and could be potentially responsible for endothelial dysfunction in vivo." (PMID 34944571, 2021). "Our previous study using FKBPL knockdown mice demonstrated strong pro-angiogenic phenotype with early signs of endothelial dysfunction." (PMID 34149611, 2021). "Our in vitro data presented here with HUVECs following overexpression of FKBPL in hypoxia restored angiogenesis to normal levels likely preventing this endothelial dysfunction." (PMID 32617576, 2021). "As disturbed angiogenesis and endothelial dysfunction are strongly implicated in T2D and CVD, we aimed to investigate the association between a novel anti-angiogenic protein, FK506-binding protein like (FKBPL), and these diseases." (PMID 33303872, 2020). "In this study, we aimed to elucidate the FKBPL-mediated mechanisms involved in regulating endothelial dysfunction induced by hypoxia or inflammation, and to determine whether AD-01 can effectively restore endothelial function under these conditions." (PMID 40069829, 2025). "Even though full FKBPL knockout has been shown to be embryonically lethal, heterozygous knockdown of FKBPL in mice does not lead to any clinically detectable adverse phenotype; however, at the proteomic level, it shows early signs of endothelial dysfunction and impaired vascular integrity." (PMID 36830764, 2023).
diabetes (4 papers, 2020 to 2023). "Both of these key functions regulate metabolism and vascular health, therefore suggesting a potentially important role for FKBPL in diabetes and the associated vascular dysfunction." (PMID 34149611, 2021). "In diabetic and gestational diabetic patients SIRT1 downregulation, along with the downregulation of FKBP prolyl isomerase-like (FKBPL), has been linked to vascular dysfunctions and pregnancy complications both in vivo and in vitro." (PMID 35328633, 2022). "FKBPL was positively correlated with age, known duration of diabetes, C-peptide level, urinary albumin to creatinine ratio (ACR), and waist to hip ratio." (PMID 33303872, 2020). "Using both diabetes and non-diabetes samples together (n = 351), FKBPL, age, SBP, cholesterol, gender and the presence of diabetes, the AUC was 0.73 (p < 0.001)." (PMID 33303872, 2020). "This might suggest that in the presence of diabetes there is a compensatory vascular mechanism, which attenuates this increase in FKBPL levels." (PMID 33303872, 2020). "The therapeutic and diagnostic role of FKBPL in this setting may warrant further investigation, particularly in the absence of diabetes." (PMID 33303872, 2020). "In conclusion, placental FKBPL and SIRT-1 expression appears to be downregulated in response to diabetes in T1D and GDM, respectively, as well as following exposure to high glucose in trophoblast cells only in low oxygen conditions." (PMID 34149611, 2021). "Furthermore, FKBPL levels were negatively correlated with characteristic metabolic parameters for T2D, glucose and HbA1c, and positively correlated with C-peptide (reflecting endogenous insulin secretion) and the duration of diabetes, in the FIELD study samples." (PMID 33303872, 2020). "In T2D, FKBPL was negatively correlated with fasting blood glucose, HbA1c and diastolic blood pressure (DBP), and positively correlated with age, known diabetes duration, waist/hip ratio, urinary albumin/creatinine ratio (ACR) and fasting C-peptide." (PMID 33303872, 2020). "Recently, it was shown that FKBPL plasma concentrations are increased in the presence of CVD and the absence of diabetes mellitus compared to healthy controls, and FKBPL is positively correlated with the echocardiographic parameters of diastolic dysfunction." (PMID 36830764, 2023). "Dysregulation in FKBPL, SIRT-1, PlGF and VEGF-R1 demonstrated in this study, albeit with differential regulation in T1D or GDM, indicate the presence of angiogenic imbalance in pregnancies complicated by diabetes involving likely different mechanisms." (PMID 34149611, 2021). "Hence, this study aimed to investigate the role of FKBPL and SIRT-1 in pre-gestational (type 1 diabetes mellitus, T1D) and gestational diabetes mellitus (GDM)." (PMID 34149611, 2021). "Therefore, in this study, placental expression of FKBPL in conjunction with SIRT-1, PlGF and VEGF-R1 was investigated in human samples from pregnant women with pre-existing diabetes (T1D), and GDM." (PMID 34149611, 2021). "As age was the only determinant of CVD in the T2D group it is possible that FKBPL is indirectly involved in cardiovascular complications of T2D, which merits further investigation into the FKBPL mechanism rather than its biomarker potential in diabetes." (PMID 33303872, 2020). "FKBPL may be a useful anti-angiogenic biomarker in CVD in the absence of diabetes and could represent a novel CVD mechanism." (PMID 33303872, 2020). "However, FKBPL’s role in the context of diabetes in pregnancy has not yet been investigated." (PMID 34149611, 2021). "Previous reports have shown that FKBPL plasma concentrations are increased in the presence of CVD and in the absence of diabetes mellitus, compared to healthy controls." (PMID 36830764, 2023). "FKBPL and SIRT-1 are critical regulators of angiogenesis, however, their roles in pregnancies affected by diabetes have not been examined before in detail." (PMID 34149611, 2021).
male infertility (4 papers, 2010 to 2025). The inability of the male to effect fertilization of an ovum after a specified period of unprotected intercourse. "Pathogenic variants in FKBPL cause male infertility by disrupting the androgen receptor (AR) signal." (PMID 34212559, 2021). "Loss of function alleles of FKBPL have also been associated with male infertility, and a mutation in FKBP4 has been associated with androgen insensitivity." (PMID 34957217, 2021). "In conclusion, we found a novel four-amino acid insertion mutation of c.229_240dup in exon 2 as well as two missense mutations in the FKBPL gene, which may cause male infertility." (PMID 34212559, 2021).
ovarian carcinoma (4 papers, 2020 to 2025). A malignant neoplasm originating from the surface ovarian epithelium. "Analysis of 1582 ovarian cancer patients of all subtypes and treatments demonstrated that low FKBPL expression was significantly associated with reduced overall survival (p = 0.021)." (PMID 31772325, 2020). "Current research on FKBPL mainly focuses on its role as a tumor growth and angiogenesis inhibitor in breast and ovarian cancers." (PMID 39749834, 2025). "ALM201 is a therapeutic peptide derived from FKBPL that has previously undergone preclinical and clinical development for oncology indications and has completed a Phase 1a clinical trial in ovarian cancer patients and other advanced solid tumours." (PMID 31772325, 2020). "An FKBPL peptide derivative, ALM-201, completed a phase I first-in-human clinical trial for ovarian cancer and other advanced solid tumors, which included two patients with EC in the safety trial group." (PMID 36295491, 2022).
Azoospermia (2 papers, 2010 to 2021). Absence of any measurable level of sperm,whereby spermatozoa cannot be observed even after centrifugation of the semen pellet. "Linkage analysis and clustering of chromosomal breakpoints in infertile men showed that FK506-binding protein like (FKBPL) gene pathogenic variants play an important role in azoospermia." (PMID 34212559, 2021). "In infertile men, no mutations of FKBP52 or FKBP6 have been found so far, but the gene for FKBP-like (FKBPL) maps to chromosome 6p21.3, an area linked to azoospermia in a group of Japanese patients." (PMID 20210997, 2010). "We found that FKBPL in humans maps to a region linked to azoospermia in a Japanese population (LOD score 3.5, p = 0.0005)." (PMID 20210997, 2010). "Linkage analysis and clustering of chromosomal breakpoints in infertile males both implicate the region containing the FKBPL gene in azoospermia." (PMID 20210997, 2010). "FKBPL maps to human chromosome 6p21.3: linkage studies in a Japanese population implicate this region specifically in azoospermia (LOD score 3.5, p = 0.0005)." (PMID 20210997, 2010). "A previous study in a Japanese population reported that FKBPL was responsible for azoospermia." (PMID 34212559, 2021).
Infertility (2 papers, 2010 to 2021). "Overall, these results indicate that mutations in FKBPL are associated or partially responsible for infertility in males and shed light on its expression and role in the normal testis." (PMID 20210997, 2010). "It has been shown that FKBPL is more highly expressed in the testis, acts as an androgen receptor regulator, and may be associated with infertility." (PMID 34212559, 2021).
agranulocytosis (1 paper, 2022). "This analysis revealed top genes, such as NOTCH4, MICA, TRIM27, PBX2, and FKBPL, as enriched in GWAS of schizophrenia, CLZ-induced agranulocytosis/granulocytopenia in treatment-resistant schizophrenia, and bipolar disorder among other psychiatric and non-psychiatric conditions." (PMID 35664466, 2022).
Anxiety (1 paper, 2023). Intense feelings of nervousness, tension, or panic often arise in response to interpersonal stresses. "The FKBPL gene is involved in the regulation of the stress response, and its malfunction has been linked to the etiology of anxiety and depression." (PMID 37375593, 2023). "We used a model of stress-induced depression and anxiety in mice to assess the potential antidepressant and anxiolytic effects of vitamins C and D. The correlation between the observed behavior and blood levels of NOx, periostin, and FKBPL was also examined." (PMID 37375593, 2023). "Several studies showed that GR plays a crucial role in the regulation of stress responses, suggesting that FKBPL might have an important role in the pathogenesis of anxiety and depression." (PMID 37375593, 2023). "The overexpression of FKBPL was connected to mental health issues, such as anxiety and depression." (PMID 37375593, 2023).
autoimmune disease (1 paper, 2024). A disorder resulting from loss of function or tissue destruction of an organ or multiple organs, arising from humoral or cellular immune responses of the individual to their own tissue constituents. "Plasma proteins with positive correlation with AS in this study were TNF, FKBPL, AGER, and ALDH5A1.TNF is a crucial cytokine playing a key role in the human immune response, involving various inflammatory and autoimmune diseases in their onset and development." (PMID 38566994, 2024).
breast tumors (1 paper, 2015). "FKBPL has known anti-angiogenic and anti-cancer stem cell activity and its over expression can slow the growth of breast tumors through stabilisation of p21, so it's prognostic ability is not surprising." (PMID 25906750, 2015).